PLPP4 (phospholipid phosphatase 4)
Description:
Magnesium-independent phospholipid phosphatase with broad substrate specificity. Preferentially catalyzes the conversion of diacylglycerol pyrophosphate into phosphatidate but can also act on phosphatidate and lysophosphatidate. Phospholipid phosphatases are involved in both the synthesis of lipids and the degradation or generation of lipid-signaling molecules like diacylglycerol.
Synonyms: DPPL2; PPAPDC1; PPAPDC1A
Tractability: Antibody: its Gene Ontology location is reachable by antibodies, with high confidence; UniProt predicts a signal peptide or a membrane-spanning region.
Gene: Protein-coding gene on chromosome 10 (120,457,227 to 120,592,065, forward strand). Ensembl gene ENSG00000203805.
Subcellular location: Membrane
Subcellular location (Human Protein Atlas): Nucleoli; Nucleoli rim; Nucleoplasm
Pathways (Reactome):
Immune System: Role of phospholipids in phagocytosis
Gene Ontology:
Molecular function: diacylglycerol diphosphate phosphatase activity; identical protein binding; phosphatidate phosphatase activity; protein binding; lysophosphatidic acid phosphatase activity
Biological process: phospholipid dephosphorylation; regulation of calcium ion import; Fc-gamma receptor signaling pathway involved in phagocytosis; phospholipid metabolic process
Cellular component: membrane; plasma membrane
Genetic constraint (gnomAD): Loss-of-function variants: 17 observed, 25.06 expected, observed/expected ratio (o/e) 0.68, 90% interval 0.46 to 1.02. The upper end of that interval is the gene's LOEUF score, 1.02, which puts it in group 4 of 6, group 1 being the genes least tolerant of losing a copy. Missense variants: 226 observed, 316.32 expected, observed/expected ratio (o/e) 0.71, 90% interval 0.64 to 0.8. Synonymous variants: 117 observed, 123 expected, observed/expected ratio (o/e) 0.95, 90% interval 0.82 to 1.11.
Homologues: Orthologues: mouse Plpp4 (99% identical), pig PLPP4 (99% identical), guinea pig PLPP4 (98% identical), chimpanzee PLPP4 (95% identical), dog PLPP4 (93% identical), rat Plpp4 (79% identical), zebrafish plpp4 (72% identical), tropical clawed frog plpp4 (68% identical), Drosophila melanogaster CG12746 (43% identical), macaque PLPP4 (39% identical), Caenorhabditis elegans plpp-1.1 (22% identical), Drosophila melanogaster laza (22% identical), and 6 more. Paralogues in human: PLPP5 (56% identical), PLPP2 (24% identical), PLPP3 (24% identical), PLPP1 (23% identical), PLPPR4 (23% identical), PLPPR3 (21% identical), PLPPR1 (19% identical), PLPPR2 (19% identical), PLPPR5 (18% identical).
Diseases named in the same sentence as PLPP4 in open-access papers:
PLPP4 is named in the same sentence as 19 diseases in open-access papers, as found by Europe PMC text mining. Sharing a sentence is not in itself a finding about the gene and the disease. The quoted sentences say what the papers report.
lung carcinoma (5 papers, 2017 to 2023). "Fluorescence-activated cell sorting, Western blotting and luciferase assays were used to identify the underlying pathway through which PLPP4 silencing mediates biological roles in lung carcinoma." (PMID 28851360, 2017). "We then investigated the mechanism underlying the inhibitory effects of PLPP4 downregulation on proliferation in lung carcinoma cells." (PMID 28851360, 2017). "Thus, our results indicate that high expression of PLPP4 is implicated in the progression of lung carcinoma via promoting the proliferation and cell cycle in lung carcinoma cells." (PMID 28851360, 2017). "Therefore, our findings indicated that high expression of PLPP4 is positively associated with advanced clinicopathological features in lung carcinoma patients." (PMID 28851360, 2017). "Therefore, our results indicated that PLPP4 may be implicated in the development and progression of lung carcinoma." (PMID 28851360, 2017). "Another investigation demonstrated that the expression of PLPP4 in lung cancer patients with a higher malignant degree was also increased." (PMID 36386793, 2022). "PLPP4 is observed in lung carcinoma tissues and cells and positively correlates with advanced clinicopathological features and poor prognosis in lung carcinoma patients." (PMID 34917513, 2021). "For example, PLPP4 depletion suppresses lung carcinoma cell proliferation and tumorigenesis via impeding the influx of intracellular Ca2+33." (PMID 32513911, 2020). "Silencing PLPP4 inhibits proliferation and cell cycle progression in vitro and tumorigenesis in vivo in lung carcinoma cells." (PMID 28851360, 2017). "The purpose of this study was to investigate the clinical significance and biological roles of PLPP4 in lung carcinoma." (PMID 28851360, 2017). "CCK-8 assays were carried out, and the results showed downregulation of PLPP4 decreased viability in lung carcinoma cells." (PMID 28851360, 2017). "Our findings further reveal that downregulating PLPP4 inhibits Ca2 + −permeable cationic channel in lung carcinoma cells." (PMID 28851360, 2017). "Luciferase assays revealed that downregulating PLPP4 or SKF 96365 repressed the transcriptional activity of NFAT in lung carcinoma cells." (PMID 28851360, 2017). "The mRNA and protein levels of PLPP4 were differentially increased in lung carcinoma cells compared with those in the WI-38 cells." (PMID 28851360, 2017). "Silencing PLPP4 inhibits the proliferation and tumorigenicity of lung carcinoma cells both in vitro and in vivo." (PMID 28851360, 2017). "In vitro and in vivo assays demonstrated that silencing PLPP4 inhibited the proliferation and cell cycle progression, and the tumorigenesis of lung carcinoma cells in subcutaneous, as well as in the lung." (PMID 28851360, 2017). "Collectively, our results suggest that silencing PLPP4 inhibits Ca2+-permeable cationic channel in lung carcinoma cells." (PMID 28851360, 2017). "In vitro and in vivo assays were performed to assess the biological roles of PLPP4 in lung carcinoma." (PMID 28851360, 2017). "To explore the biological roles of PLPP4 in lung carcinoma, we first examined PLPP4 expression levels in the normal lung epithelial cell line WI-38 and seven lung carcinoma cell lines by real-time PCR and Western blotting." (PMID 28851360, 2017). "Our results further reveal that PLPP4 silencing inhibits Ca2+-permeable cationic channel, suggesting that downregulation of PLPP4 inhibits proliferation and tumorigenesis in lung carcinoma cells via reducing the influx of intracellular Ca2+." (PMID 28851360, 2017). "Our results further verify that overexpression of PLPP4 is observed in lung carcinoma tissues and cells and positively correlates with advanced clinicopathological features and poor prognosis in lung carcinoma patients." (PMID 28851360, 2017).
lung carcinoma (continued). "In this study, by analyzing the expression levels of LPP family proteins in lung carcinoma RNA expression profile datasets from The Cancer Genome Atlas (TCGA), we found that PLPP4 is dramatically elevated compared with other LPPs in lung carcinoma tissues." (PMID 28851360, 2017). "As the highest expression of PLPP4 was in A549 and Calu-3 cells, we constructed PLPP4-stably suppressing A549 and Calu-3 lung carcinoma cells by endogenously knocking down PLPP4 via retroviral infection." (PMID 28851360, 2017). "Fluorescence-activated cell sorting (FACS) analysis showed that silencing PLPP4 decreased intracellular Ca2+ in lung carcinoma cells, which was more obvious in cells treated with SKF 96365, a novel inhibitor of receptor-mediated Ca2+ entry (5 μm, 24 h)." (PMID 28851360, 2017). "Collectively, these findings indicate that PLPP4 silencing inhibits the tumorigenesis and lung colonization capabilities of lung carcinoma cells." (PMID 28851360, 2017). "Taken together, these findings demonstrated that silencing PLPP4 inhibits the proliferation ability of lung carcinoma cells." (PMID 28851360, 2017). "PLPP4 expression was examined in 8 paired lung carcinoma tissues by real-time PCR and in 265 lung carcinoma tissues by immunohistochemistry (IHC)." (PMID 28851360, 2017). "Subsequent analysis of PLPP4 expression in lung carcinoma datasets from TCGA and ArrayExpress showed that PLPP4 expression was upregulated in ADC tissues compared that in the ANT and was further increased in SQC tissues." (PMID 28851360, 2017). "Overexpression of PLPP4 was further observed in our lung carcinoma tissues and cells and positively correlated with advanced clinicopathological features and poor prognosis." (PMID 28851360, 2017). "Collectively, these results indicated that downregulation of PLPP4 inhibits proliferation in lung carcinoma cells via eliciting cell cycle arrest." (PMID 28851360, 2017). "High expression of PLPP4 significantly correlated with advanced clinicopathological features, and poor overall and progression-free survival in lung carcinoma patients." (PMID 28851360, 2017). "Collectively, these results from publicly available lung carcinoma datasets suggest that the overexpression of PLPP4 correlates with poor prognosis and progression status in lung carcinoma patients." (PMID 28851360, 2017). "Statistical analysis was performed to evaluate the clinical correlation between PLPP4 expression and clinicopathological features and survival in lung carcinoma patients." (PMID 28851360, 2017). "Flow cytometry analysis showed that silencing PLPP4 dramatically decreased the percentage of cells in the S phase and increased that of cells in the G1/G0 phase, indicating that silencing PLPP4 induced G1/S arrest in lung carcinoma cells." (PMID 28851360, 2017). "In this study, through analyzing the expression levels of LPPs proteins in the lung carcinoma RNA expression profile datasets from TCGA, we first found that PLPP4 was considerably elevated compared with other LPPs in lung carcinoma tissues." (PMID 28851360, 2017). "PLPP4 (phospholipid phosphatase 4) could promote proliferation and tumorigenesis in lung carcinoma cells, and serve as a potential therapeutic target for glioma and PAAD." (PMID 37006317, 2023). "Taken together, our findings indicate that PLPP4 plays an important role in the progression of lung carcinoma and suggest that PLPP4 may serve as a potential target for human lung carcinoma treatment." (PMID 28851360, 2017). "Moreover, silencing PLPP4 inhibits the proliferation, cell cycle progression, tumorigenicity and lung metastasis abilities of lung carcinoma cells both in vitro and in vivo." (PMID 28851360, 2017). "In the current study, we first revealed that PLPP4 was elevated in lung carcinoma tissues." (PMID 28851360, 2017). "Therefore, our results elucidate the oncogenic role of PLPP4 in lung carcinoma via elevating intracellular Ca2+." (PMID 28851360, 2017).
lung carcinoma (continued). "In addition, our findings reveal that downregulating PLPP4 inhibits Ca2+-permeable cationic channel in lung carcinoma cells." (PMID 28851360, 2017). "Our findings indicate that inhibition of PLPP4 may be used as a novel therapeutic strategy in the treatment of lung carcinoma." (PMID 28851360, 2017). "Moreover, silencing PLPP4 repressed the proliferation, tumorigenicity and lung metastasis abilities of lung carcinoma cells both in in vitro and in vivo, as well as inhibited Ca2+-permeable cationic channel in lung carcinoma cells." (PMID 28851360, 2017). "PLPP4 expression levels in 57 paired ADC tissues and 51 paired SQC tissues from lung carcinoma TCGA profile were analyzed and the results revealed that PLPP4 expression was dramatically elevated in both ADC and SQC tissues compared with that in the respective ANT." (PMID 28851360, 2017). "Statistical analysis demonstrated that high expression of PLPP4 significantly and positively correlated with clinicopathological features, including pathological grade, T category and stage, and poor overall and progression-free survival in lung carcinoma patients." (PMID 28851360, 2017). "Our results indicate that PLPP4 may hold promise as a novel marker for the diagnosis of lung carcinoma and as a potential therapeutic target to facilitate the development of novel treatment for lung carcinoma." (PMID 28851360, 2017). "Therefore, our findings indicate that PLPP4 plays an important role in lung carcinoma." (PMID 28851360, 2017). "Therefore, our data may lead us to further in vivo studies, namely, inhibition of PLPP4 may be used as a complementary strategy in the treatment of lung carcinoma." (PMID 28851360, 2017). "Furthermore, subcutaneous and lung colonization models showed that downregulating PLPP4 dramatically inhibited the tumorigenesis of lung carcinoma cells in a mouse model, indicating that PLPP4 may hold potential applicable value as a therapeutic target against lung carcinoma." (PMID 28851360, 2017). "Real-time PCR and Western blot analysis revealed that silencing PLPP4 repressed the mRNA and protein expression levels of critical cell cycle regulators of the G1/S checkpoint CCND1, CCNA2 and CCNB1 in lung carcinoma cells." (PMID 28851360, 2017). "In the current study, our results found that silencing PLPP4 effectively reduced intracellular Ca2+ and S54 phosphorylated levels of NFAT1, which further inhibited the proliferation and tumorigenesis in lung carcinoma cells." (PMID 28851360, 2017). "In-depth analysis of lung carcinoma TCGA and ArrayExpress datasets showed that ADC or SQC patients with high expression of PLPP4 displayed poor overall and progression-free survival rates, but not for the SQC dataset from ArrayExpress." (PMID 28851360, 2017).
gastric cancer (3 papers, 2018 to 2024). A primary or metastatic malignant neoplasm involving the stomach. "Recent studies have found that PLPP4 can promote the invasion and migration in LUAD and gastric cancer." (PMID 34917513, 2021).
breast carcinoma (2 papers, 2017 to 2024). "PLPP4 was first identified by DNA microarray, cDNA dot blot analysis, and reverse transcription-PCR techniques in paired breast cancer tissues." (PMID 28851360, 2017). "Furthermore, Manzano and colleagues reported that PLPP4 was upregulated in only the estrogen receptor (ER)-ERBB2+ subgroup, but not in other subtypes of breast cancer, suggesting a specific role of PLPP4 in ER-ERBB2+ subtypes." (PMID 28851360, 2017).
glioma (2 papers, 2021 to 2023). A benign or malignant brain and spinal cord tumor that arises from glial cells (astrocytes, oligodendrocytes, ependymal cells). "Further, we analyzed the correlation between PLPP4 and other genes, and the heatmap showed genes that are positively correlated with PLPP4 and genes which are negatively associated with PLPP4 in glioma." (PMID 34917513, 2021). "And for the prognostic value of the DNA methylation of PLPP4, 15 CpGs of PLPP4, 3 CpGs of PLPP4 were significantly associated with prognosis in glioma and PAAD patients." (PMID 34917513, 2021). "ROC curve analysis was used to analyze the diagnostic effect of PLPP4 expression on glioma patients." (PMID 34917513, 2021). "The present study explored possible molecular mechanisms and potential diagnostic and prognostic biomarker-PLPP4 of glioma and PAAD." (PMID 34917513, 2021). "Therefore, our findings indicated that high expression of PLPP4 was positively associated with advanced clinicopathological features in glioma patients." (PMID 34917513, 2021). "Therefore, our results indicated that PLPP4 might be implicated in the development and progression of glioma and PAAD." (PMID 34917513, 2021). "Our study also found that the level of DNA methylation of PLPP4 was related to the survival of glioma and PAAD." (PMID 34917513, 2021). "High expression of PLPP4 significantly correlated with advanced clinicopathological features and poor overall and progression-free survival in the glioma and PAAD patients." (PMID 34917513, 2021). "Statistical analysis from TCGA demonstrated that high expression of PLPP4 significantly and positively correlated with clinicopathological features, including pathological grade and poor overall survival in glioma and PAAD patients." (PMID 34917513, 2021). "In this study, by analyzing the expression levels of LPP family proteins in tumor RNA expression profile datasets from The Cancer Genome Atlas (TCGA), we found that PLPP4 is dramatically elevated compared with other LPPs in the glioma and PAAD tissues." (PMID 34917513, 2021). "Our results also showed that overexpression of PLPP4 promoted the invasiveness of glioma LN229 cells, while the number of cells in the shRNA-PLPP4 group was reduced, and the invasiveness was reduced by 55.2% through the transwell assay." (PMID 34917513, 2021). "We further performed Immunohistochemical analysis to investigate the effects of PLPP4 on the tumorigenic activity of the glioma and PAAD patients and found that PLPP4 showed high expression in the glioma and PAAD patients." (PMID 34917513, 2021). "Based on the expression level of PLPP4, we performed a subgroup analysis of tumor grade, age, race, gender, recurrence, and metastasis for glioma." (PMID 34917513, 2021). "Collectively, these results from publicly available cancer datasets suggest that the overexpression of PLPP4 correlates with poor prognosis and progression status in glioma, LUAD, and PAAD patients." (PMID 34917513, 2021). "The prognostic value of DNA methylation of PLPP4 in glioma, LUAD, and PAAD was analyzed by MethSurv." (PMID 34917513, 2021). "Taken together, these findings demonstrated that silencing PLPP4 inhibits the proliferation, migration, and invasion ability of the glioma and PAAD cells." (PMID 34917513, 2021). "PLPP4 expression was primarily detected in the cytoplasm, and the staining intensity of PLPP4 was increased in glioma tissues compared with normal tissues." (PMID 34917513, 2021). "In conclusion, this work provided evidence of the values of PLPP4 as clinical biomarkers and therapeutic targets in glioma and PAAD." (PMID 34917513, 2021). "In addition, our findings reveal that DNA methylation of PLPP4 is related to survival probability in glioma and PAAD patients." (PMID 34917513, 2021). "In general, the PLPP4 signature performed well at predicting the overall survival of glioma." (PMID 34917513, 2021). "In the current study, we first revealed that PLPP4 was elevated in the glioma and PAAD." (PMID 34917513, 2021).